IRF6 (interferon regulatory factor 6)
Description:
Probable DNA-binding transcriptional activator. Key determinant of the keratinocyte proliferation-differentiation switch involved in appropriate epidermal development (By similarity). Plays a role in regulating mammary epithelial cell proliferation (By similarity). May regulate WDR65 transcription (By similarity).
Synonyms: OFC6; VWS1; LPS; PIT; PPS; PPS1; VWS
Tractability: PROTAC: UniProt records ubiquitination sites on it; ubiquitination databases record sites on it.
Gene: Protein-coding gene on chromosome 1 (209,785,254 to 209,806,217, reverse strand). Ensembl gene ENSG00000117595.
Subcellular location: Nucleus; Cytoplasm
Subcellular location (Human Protein Atlas): Cytosol; Nucleoplasm
Pathways (Reactome):
Immune System: Interferon alpha/beta signaling; Interferon gamma signaling
Gene Ontology:
Molecular function: protein binding; sequence-specific DNA binding; sequence-specific double-stranded DNA binding; DNA binding; DNA-binding transcription factor activity; DNA-binding transcription factor activity, RNA polymerase II-specific; RNA polymerase II cis-regulatory region sequence-specific DNA binding; DNA-binding transcription activator activity, RNA polymerase II-specific; transcription cis-regulatory region binding
Biological process: negative regulation of cell population proliferation; positive regulation of transcription by RNA polymerase II; immune system process; mammary gland epithelial cell differentiation; positive regulation of DNA-templated transcription; regulation of transcription by RNA polymerase II; regulation of DNA-templated transcription
Cellular component: cytoplasm; cytosol; extracellular exosome; chromatin; nucleus; apical part of cell
Genetic constraint (gnomAD): Loss-of-function variants: 5 observed, 49.14 expected, observed/expected ratio (o/e) 0.1, 90% interval 0.052 to 0.21. The synonymous counts are far from expectation, so gnomAD's model fits this gene poorly and the ratio says little. Missense variants: 342 observed, 604.39 expected, observed/expected ratio (o/e) 0.57, 90% interval 0.52 to 0.62. Synonymous variants: 173 observed, 224.95 expected, observed/expected ratio (o/e) 0.77, 90% interval 0.68 to 0.87.
Gene-disease validity (ClinGen):
ClinGen rates the evidence that IRF6 causes each of these diseases.
IRF6-related condition (autosomal dominant): Definitive. Van der Woude syndrome, popliteal pterygium syndrome, cleft lip with or without palate, or a spectrum of one or two of those conditions in which the cause of the disease is a mutation in the IRF6 gene.
Homologues: Orthologues: chimpanzee IRF6 (100% identical), macaque IRF6 (100% identical), guinea pig IRF6 (99% identical), pig IRF6 (99% identical), rabbit IRF6 (99% identical), rat Irf6 (98% identical), dog IRF6 (98% identical), mouse Irf6 (98% identical), tropical clawed frog irf6 (78% identical), tropical clawed frog irf6.2 (77% identical), zebrafish irf6 (67% identical). Paralogues in human: IRF5 (51% identical), IRF4 (27% identical), IRF8 (26% identical), IRF3 (25% identical), IRF7 (24% identical), IRF9 (21% identical), IRF2 (16% identical), IRF1 (14% identical).
Diseases named in the same sentence as IRF6 in open-access papers:
IRF6 is named in the same sentence as 100 diseases in open-access papers, as found by Europe PMC text mining. Sharing a sentence is not in itself a finding about the gene and the disease. The quoted sentences say what the papers report.
van der Woude syndrome (54 papers, 2006 to 2025). Van der Woude syndrome (VWS) is a rare congenital genetic dysmorphic syndrome characterized by paramedian lower-lip fistulae, cleft lip with or without cleft palate, or isolated cleft palate. "The most common syndromic form is Van der Woude syndrome, resulting from mutations in the IRF6 gene (locus 1q32-q41)." (PMID 41378467, 2025). "IRF6 mutations, for instance, cause Van der Woude syndrome with clear autosomal dominant inheritance and ∼96% penetrance." (PMID 41378467, 2025). "For example, IRF6 was first identified as the gene associated with Van der Woude syndrome, and subsequent knockout studies in mice revealed its critical role in periderm function during palatogenesis." (PMID 40918684, 2025). "In humans, heterozygous mutations in IRF6 are associated with van der Woude syndrome, a condition associated with facial malformations due to developmental dysmorphogenesis." (PMID 38378697, 2024). "Remarkably, the removal of the uORF upstream of IRF6 during the Van der Woude syndrome-associated mutation via deaminase-enabled recoding of RNA (DECOR)-mediated RNA editing reportedly rescues IRF6 expression." (PMID 39525088, 2024). "The IRF6 gene is associated with van der Woude syndrome (VWS) and Bartsocas–Papas congenital anomaly syndrome." (PMID 37762190, 2023). "Studies in mammals have shown that IRF6 regulates epidermal proliferation and differentiation, and mutations in the IRF6 gene can lead to Van der Woude syndrome (VWS) and popliteal pterygium syndrome (PPS), but is not relevant with IFN production." (PMID 36503433, 2022). "In humans, rare IRF6 variants are causal for Van der Woude syndrome (VWS, OMIM: 119300) and Popliteal Pterygium syndrome (PPS, OMIM: 119500), which are characterized by the presence of orofacial clefts, lip pits as well as cutaneous and limb defects." (PMID 34660580, 2021). "Mutations in IRF6 cause two common forms of syndromic cleft, known as Van der Woude Syndrome (VWS) and popliteal pterygium syndrome." (PMID 33195260, 2020). "For example, variants of IRF6, a known regulator of human palatogenesis, are implicated both in syndromic (Van der Woude syndrome) and non-syndromic CL/P." (PMID 31471293, 2019). "Mutations in IRF6 have been shown to contribute to the development of Van der Woude syndrome (VWS) and popliteal pterygium syndrome (PPS)." (PMID 30515152, 2018). "‘Interferon regulatory factor 6’ (IRF6) on chromosome 1q32.2 is an example of a gene that was first reported to cause a clefting syndrome (Van der Woude syndrome) and that was later shown to be involved in isolated clefts." (PMID 28877219, 2017). "In human, mutations in IRF6 cause two orofacial clefting syndromes, Van der Woude syndrome (VWS) and popliteal pterygium syndrome (PPS)." (PMID 27035130, 2016). "IRF6 can be considered as the second gene most likely playing a role in the combined OFC–TA phenotype since it is the causative gene of van der Woude syndrome, whose typical features are OFCs, TA and lip pits." (PMID 27699475, 2016). "IRF4 is a lymphocyte specific factor and the IRF6 gene is largely uncharacterised except for an association with van-der-Woude-syndrome." (PMID 25856589, 2015). "The protein encoded by IRF6 contribute to the development of van der Woude’s syndrome and popliteal pterygium syndrome, both of which are characterized by various degrees of cleft lip, cleft lip and palate, and CPO." (PMID 26322076, 2015). "Mutations in IRF6 lead to isolated and syndromic forms of cleft lip and palate, most notably Van der Woude syndrome (VWS) and Popliteal Ptyerigium Syndrome (PPS)." (PMID 23451037, 2013). "IRF6 mutations, in addition to causing Van der Woude syndrome, can cause popliteal pterygium syndrome, an autosomal dominant disorder characterized by orofacial anomalies including lower lip pits, cleft lip and/or palate, syngnathia, syndactyly, webbing of the lower limbs, and genital abnormalities." (PMID 41075272, 2025).
van der Woude syndrome (continued). "Numerous studies have shown that a gene whose polymorphisms may be associated with NSCL/P is the IRF6 gene, mutations of which are responsible for van der Woude syndrome (VWS)." (PMID 37020525, 2023). "As with Irf6, mutations in Grhl3 cause Van der Woude syndrome." (PMID 37169019, 2023). "Irf6 has been suggested to activate Grhl3 in the zebrafish periderm and mutations in Irf6 or Grhl3 are associated with neural crest defects (cleft-lip/palate) characteristic of Van der Woude syndrome." (PMID 35088714, 2022). "Loss-of-function mutations in interferon regulatory factor-6 (IRF6) are responsible for about 70% of cases of Van Der Woude Syndrome (VWS), an autosomal dominant developmental disorder characterized by pits and/or sinuses of the lower lip and cleft lip, cleft palate, or both." (PMID 32582293, 2020). "Although the role of IRF6 in immune response is undefined, IRF6 gene mutation in humans could lead to genetic disorders such as Van der Woude syndrome and popliteal pterygium syndrome." (PMID 30147694, 2018). "Mutations in IRF6 are linked to Van der Woude Syndrome (VWS, OMIM 119300), Popliteal Pterygium Syndrome (PPS, OMIM 119500), and non-syndromic orofacial cleft lip (CL/P, OMIM 119530), ]." (PMID 38370976, 2024). "Van der Woude syndrome (VWS) is an autosomal dominant disorder responsible for 2% of all syndromic orofacial clefts (OFCs), with IRF6 being the primary causal gene (70%)." (PMID 36936396, 2023). "Van der Woude syndrome (VWS) is an autosomal dominant syndrome due to mutation of a gene located in the long arm of chromosome 1 (1q32.3-q4) called the interferon regulatory factor-6 (IRF6) gene." (PMID 34430173, 2021). "Mutations in IRF6 cause Van der Woude Syndrome (VWS), which is the most common malformation of syndromic orofacial clefts in humans." (PMID 32108996, 2020). "Mutations in human IRF6 give rise to Van der Woude syndrome (VWS), a developmental condition, and popliteal pterygium syndrome (PPS), which is a less severe form of BPS." (PMID 32923402, 2020). "IRF6-related disorders are a group of inherited disorders associated with heterozygous pathogenic variants in IRF6, including Van der Woude syndrome (VWS, OMIM:119300) and popliteal pterygium syndrome (PPS, OMIM:119500)." (PMID 29523099, 2018). "Mutations in Irf6 cause two allelic orofacial clefting syndromes in humans: Van der Woude syndrome (VWS) and popliteal pterygium syndromes (PPS)." (PMID 29973266, 2018). "Mutations in IRF6 are associated with Van der Woude Syndrome (VWS, OMIM #119300) and Popliteal Pterygium Syndrome (PPS, OMIM #119500)." (PMID 28593555, 2017). "Interferon regulatory factor 6 (IRF6) is one such candidate gene, and mutations in IRF6 cause Van der Woude syndrome (VWS, [MIM 119300]), the most common type of syndromic OFC, or popliteal pterygium syndrome (PPS, [MIM 119500])." (PMID 27459192, 2016). "It is recognized that PPS and van der Woude syndrome (VWS) are allelic, based on mutations in the IRF6 gene causing either PPS or VWS." (PMID 27252970, 2015). "IRF6 belongs to a gene family (IRFs) of transcription factors that regulate expression of interferons-α and –β after viral infections, and is a causal gene for Van der Woude’s syndrome which includes cleft lip/palate, pits on the lower lip, and tooth agenesis as part of the clinical phenotype." (PMID 23029012, 2012). "The associated malformations addressed to molecular genetic investigations revealing an interferon regulatory factor 6 (IRF6)-related disorder (van der Woude syndrome/popliteal pterygium syndrome)." (PMID 35906647, 2022). "The most common orofacial cleft syndrome is the van der Woude syndrome (VWS), which found 2% of all syndromic CL/P, caused by mutation or deletion of the IRF6 gene in 68% of the cases." (PMID 33732167, 2021). "It is a study on IRF6 sequencing of six Van der Woude Syndrome families in the Chinese Han population." (PMID 32108996, 2020).
van der Woude syndrome (continued). "Alternatively, some patients with Van der Woude syndrome have a mutation in the GRHL3 gene, a downstream target of IRF6." (PMID 31471293, 2019). "The interferon regulatory factor 6 (IRF6) gene is consistently associated with non-syndromic CLP in multiple studies and is also the causative agent of van der Woude syndrome, the most common syndromic cause of cleft lip." (PMID 24400297, 2013). "SNPs in genes involved with syndromes were previously associated with a variety of facial measurements, for example, genes such as FGFR1 (e.g., Pfeiffer syndrome and Kallmann syndrome), IRF6 (e.g., Van der Woude syndrome), and RUNX2 (e.g., cleidocranial dysplasia syndrome)." (PMID 40303982, 2025). "The Interferon Regulatory Factor 6 (IRF6) gene is one of the earliest sustainability genes for nonsyndromic cleft lip identified and proved to be the causative gene for Van der Woude syndrome." (PMID 37628654, 2023). "Individuals with mutations in either of the epithelial transcription factors grainyhead-like transcription factor 3 (GRHL3) and interferon regulatory factor 6 (IRF6), detected in families with Van der Woude syndrome, tend to present with CLP." (PMID 30760477, 2019).
cleft lip (44 papers, 2009 to 2025). Congenital defect in the upper lip where the maxillary prominence fails to merge with the merged medial nasal prominences. "We focused on the previously characterised rare non-coding 350dupA mutation at the IRF6 locus that is linked to cleft lip formation." (PMID 39762235, 2025). "Studies have identified the IRF6 gene as a key transcription factor associated with the pathogenesis of cleft lip and palate pathogenesis." (PMID 38533046, 2024). "A meticulous review of existing literature disclosed a significant association between diverse mutations within the IRF6 gene and the onset of both cleft lip/palate and VWS." (PMID 38903762, 2024). "We focused on the IRF6 transcription factor because it is one of the most commonly associated genes with cleft lip and palate, based on recent genome-wide association studies and studies carried out over a decade." (PMID 38533046, 2024). "Variants within the gene encoding for the transcription factor Interferon Regulatory Factor 6 (IRF6) are associated with syndromic and non-syndromic Cleft Lip/Palate (CLP) cases." (PMID 34660580, 2021). "In contrast, 2.7% of these mice had a cleft lip, which supports the high expression level of IRF6 as a risk for CLO." (PMID 31609978, 2019). "Human genetic studies showed that mutations in IRF6 lead to cleft lip and palate and mandibular abnormalities." (PMID 28769044, 2017). "Whereas mutations in IRF6 cause syndromic orofacial clefting, IRF6 polymorphisms are associated with non-syndromic cleft lip and/or palate (NSCL/P, OMIM #119530)." (PMID 28593555, 2017). "It was previously reported that one third of the population carries a genetic variant in an IRF6 enhancer associated with increased risk for cleft lip and palate." (PMID 27035130, 2016). "The rs642961 SNP in the IRF6 gene (a known risk factor of non-syndromic cleft lip/palate) was found to strongly predict normal lip shape variation in Han Chinese females but not males." (PMID 27584156, 2016). "The final known disease-associated non-coding variant we studied was a well-established polymorphic change associated with cleft lip, in an upstream regulatory element controlling the expression of Interferon Regulatory Factor 6 (IRF6)." (PMID 26030420, 2015). "In particular, one SNP, a known risk factor of non-syndromic cleft lips/palates, rs642961 in the IRF6 gene, was validated to strongly predict normal lip shape variation in female Han Chinese." (PMID 24339768, 2013). "The association between IRF6 gene and cleft lip and palate has also been independently replicated in many populations." (PMID 23510002, 2013). "In contrast to other studies, all of which showed association of IRF6 comparing only the three major cleft categories (cleft lip, cleft lip/palate and cleft palate), we only found positive association when comparing cleft subphenotypes with controls." (PMID 23029012, 2012). "Of all the genetic studies with cleft lip/palate, the association with IRF6 is certainly the most consistent, and has been consistently replicated in multiple populations." (PMID 23029012, 2012). "Furthermore, reduced canonical Wnt signaling compromised p63/IRF6 activity, resulting in higher proliferation and decreased cell death, which in turn caused the persistence of the epithelial seam and cleft lip development." (PMID 38227085, 2024). "An IRF6 SNP may play a major role in the pathogenesis and risk of developing non-syndromic cleft lip +/− palate in a South Indian population." (PMID 37238140, 2023). "In addition, an association of interaction between the IRF6 gene and maternal FA intake with non-syndromic cleft lip/palate in Mexican Mestizos was found." (PMID 36032143, 2022). "Taken together, these findings suggest individual IRF6 status may be an important tool to revisit recurrence risk estimates for cleft lip/palate." (PMID 23029012, 2012).